DCTN5 (dynactin subunit 5)
Description:
Part of the dynactin complex that activates the molecular motor dynein for ultra-processive transport along microtubules.
Synonyms: MGC3248; p25
Tractability: PROTAC: ubiquitination databases record sites on it; its protein half-life has been measured.
Gene: Protein-coding gene on chromosome 16 (23,641,381 to 23,677,472, forward strand). Ensembl gene ENSG00000166847.
Subcellular location: Cytoplasm, cytoskeleton; Chromosome, centromere, kinetochore
Subcellular location (Human Protein Atlas): Nuclear membrane; Nucleoplasm
Pathways (Reactome):
Vesicle-mediated transport: COPI-independent Golgi-to-ER retrograde traffic; COPI-mediated anterograde transport
Cellular responses to stimuli: HSP90 chaperone cycle for steroid hormone receptors (SHR) in the presence of ligand
Immune System: MHC class II antigen presentation
Gene Ontology:
Molecular function: protein binding
Cellular component: centrosome; cytosol; dynactin complex; cytoskeleton
Genetic constraint (gnomAD): Loss-of-function variants: 10 observed, 18.86 expected, observed/expected ratio (o/e) 0.53, 90% interval 0.33 to 0.9. The upper end of that interval is the gene's LOEUF score, 0.9, which puts it in group 3 of 6, group 1 being the genes least tolerant of losing a copy. Missense variants: 144 observed, 214.9 expected, observed/expected ratio (o/e) 0.67, 90% interval 0.58 to 0.77. Synonymous variants: 62 observed, 78.71 expected, observed/expected ratio (o/e) 0.79, 90% interval 0.64 to 0.97.
Homologues: Orthologues: chimpanzee DCTN5 (100% identical), dog DCTN5 (100% identical), guinea pig DCTN5 (100% identical), macaque DCTN5 (100% identical), pig DCTN5 (100% identical), rabbit DCTN5 (100% identical), mouse Dctn5 (99% identical), rat Dctn5 (99% identical), zebrafish dctn5 (96% identical), tropical clawed frog dctn5 (89% identical), Drosophila melanogaster DCTN5-p25 (59% identical), Caenorhabditis elegans dnc-5 (44% identical).
Diseases named in the same sentence as DCTN5 in open-access papers:
DCTN5 is named in the same sentence as 9 diseases in open-access papers, as found by Europe PMC text mining. Sharing a sentence is not in itself a finding about the gene and the disease. The quoted sentences say what the papers report.
bipolar disorder (2 papers, 2011 to 2017). A disorder of the brain that causes unusual shifts in mood, energy, activity levels and the ability to carry out day-to-day tasks. "DCTN5 also interacts with DISC1 gene (Disrupted in schizophrenia 1), a gene associated with bipolar disorder in several studies." (PMID 28283021, 2017).
schizophrenia (2 papers, 2011 to 2023). A major psychotic disorder characterized by abnormalities in the perception or expression of reality. "Here these two proteins, RAB6B and RAB7A, were found altered in the prefrontal cortex in schizophrenia with an interaction with both ACTR1A and DCTN5." (PMID 37033658, 2023).
psychiatric disorder (1 paper, 2020). A disorder characterized by behavioral and/or psychological abnormalities, often accompanied by physical symptoms. "In a similar manner to CTSD-deficient mice, knockdown of DCTN5 in a murine model of psychiatric disorder susceptibility genes also results in abnormal mania-related hyperactivity." (PMID 32325768, 2020).
DCTN5 also shares sentences with these, for which no sentence is quoted: cancer (2 papers); breast carcinoma (1); infection (1); lung carcinoma (1); neurodegenerative disease (1); pneumococcal meningitis (1).